LRIG1 (leucine rich repeats and immunoglobulin like domains 1)
Description:
Acts as a feedback negative regulator of signaling by receptor tyrosine kinases, through a mechanism that involves enhancement of receptor ubiquitination and accelerated intracellular degradation.
Synonyms: LIG-1; LIG1; DKFZP586O1624
Tractability: Antibody: UniProt places it where antibodies can reach, with high confidence; its Gene Ontology location is reachable by antibodies, with high confidence; UniProt predicts a signal peptide or a membrane-spanning region. PROTAC: ubiquitination databases record sites on it; its protein half-life has been measured.
Gene: Protein-coding gene on chromosome 3 (66,378,794 to 66,501,263, reverse strand). Ensembl gene ENSG00000144749.
Subcellular location: Cell membrane
Subcellular location (Human Protein Atlas): Cytosol
Pathways (Reactome):
Signal Transduction: Negative regulation of MET activity; Signaling by EGFR
Developmental Biology: Differentiation of Keratinocytes in Interfollicular Epidermis in Mammalian Skin
Gene Ontology:
Molecular function: protein binding; signaling receptor activity
Biological process: sensory perception of sound; otolith morphogenesis
Cellular component: plasma membrane
Genetic constraint (gnomAD): Loss-of-function variants: 49 observed, 96.24 expected, observed/expected ratio (o/e) 0.51, 90% interval 0.4 to 0.65. The synonymous counts are far from expectation, so gnomAD's model fits this gene poorly and the ratio says little. Missense variants: 1,643 observed, 1,458.8 expected, observed/expected ratio (o/e) 1.13, 90% interval 1.08 to 1.17. Synonymous variants: 771 observed, 601.83 expected, observed/expected ratio (o/e) 1.28, 90% interval 1.21 to 1.36.
Homologues: Orthologues: chimpanzee LRIG1 (99% identical), macaque LRIG1 (97% identical), guinea pig LRIG1 (86% identical), dog LRIG1 (85% identical), rabbit LRIG1 (85% identical), pig LRIG1 (84% identical), mouse Lrig1 (83% identical), rat Lrig1 (83% identical), tropical clawed frog lrig1 (61% identical), zebrafish lrig1 (57% identical), Drosophila melanogaster lbk (31% identical). Paralogues in human: LRIG3 (49% identical), LRIG2 (47% identical), LGR6 (19% identical), LGR5 (17% identical), LGR4 (17% identical), TRIL (15% identical), CHADL (14% identical), CPN2 (13% identical), LRRC24 (12% identical), ELFN1 (12% identical), ELFN2 (11% identical), LRRTM2 (11% identical), and 10 more.
Diseases named in the same sentence as LRIG1 in open-access papers:
LRIG1 is named in the same sentence as 97 diseases in open-access papers, as found by Europe PMC text mining. Sharing a sentence is not in itself a finding about the gene and the disease. The quoted sentences say what the papers report.
glioma (26 papers, 2013 to 2025). A benign or malignant brain and spinal cord tumor that arises from glial cells (astrocytes, oligodendrocytes, ependymal cells). "Lrig1 is highly expressed in gliomas and importantly, polymorphisms have been identified that are risk alleles for patients with GBM, which suggests some functional role in gliomagenesis." (PMID 36420140, 2022). "In glioma, loss of LRIG1 results in very aggressive tumors, though the ectopic LRIG1 expression causes decreased tumor cell proliferation by negatively regulating the oncogenic EGFR mutant EGFRvIII, which is often highly expressed in glioblastoma." (PMID 33786987, 2021). "The loss of a functional Lrig1 allele, which resulted in reduced mRNA and protein expression of Lrig1, promoted the progression of gliomas from grade II/III to grade IV." (PMID 29391393, 2018). "Recently, a genome-wide association study showed that a single nucleotide polymorphism (SNP) —rs11706832—in intron 2 of the human LRIG1 (Leucine-rich repeats and immunoglobulin-like domains 1) gene is associated with susceptibility to glioma." (PMID 29391393, 2018). "Moreover, our study contributes to the growing body of evidence associating LRIG1 with glioma pathogenesis, corroborating previous research highlighting LRIG1’s inhibitory effects on EGFR expression and downstream signaling pathways." (PMID 38790164, 2024). "Lrig1 has been shown to be more highly expressed in gliomas than other human cancers and genome-wide association studies have identified a risk allele (rs11706832) associated with glioma susceptibility." (PMID 36420140, 2022). "Thus, for the first time, changes in physiological Lrig1 expression have been linked to gliomagenesis, whereby the SNP rs11706832 may affect glioma risk by regulating LRIG1 expression." (PMID 29391393, 2018). "However, the mechanism by which rs11706832 affects glioma risk remains unknown; additionally, it is unknown whether the expression levels of LRIG1 are a relevant determinant of gliomagenesis." (PMID 29391393, 2018). "LRIG1 was less expressed in glioma compared to peritumoral tissue with additional decrease with ascending tumors grade." (PMID 41201961, 2025). "Because of these contrasting roles, the expression of LRIG1-3 was examined across different grades of glioma, between primary and secondary glioblastoma and with focus on chemotherapy treatment." (PMID 41201961, 2025). "In this study we examined the expression of LRIG1-3 in different grades of gliomas, the differences in expression levels between primary and secondary GBMs and the influence of chemotherapy on expression levels." (PMID 41201961, 2025). "We also observed a negative correlation between the expression and WHO tumor grade, thus, LRIG1 expression was significantly higher in low compared to high grade glioma." (PMID 41201961, 2025). "LRIG1 protein level was found to be significantly lower in glioma compared to control tissue (0.096 ± 0.072 vs. 0.606 ± 0.303, p = 0.0004), whereas LRIG1 gene transcription tended to be slightly higher (1.046 ± 0.769 vs. 0.808 ± 0.354, n.s.)." (PMID 41201961, 2025). "By negatively regulating EGFR, LRIG1 normally promotes apoptosis and inhibits proliferation and invasion of glioma cells as well as tumor angiogenesis." (PMID 41201961, 2025). "The expression of LRIG1 in different grades of glioma was quantified using qPCR, western blot (WB) and immunofluorescence." (PMID 41201961, 2025). "To summarize, we demonstrated that LRIG1 protein expression was significantly decreased in gliomas compared to peritumoral control tissue." (PMID 41201961, 2025). "In contrast to LRIG1, the less studied LRIG2 is believed to be a tumor promoter that enhances the development of glioma and is associated with higher grades." (PMID 41201961, 2025). "Comparison of the individual astrocytoma grades revealed a significantly decreased LRIG1 gene transcription in grade III compared to grade II glioma (1.520 ± 1.173 vs. 2.868 ± 1.862, p = 0.0096)." (PMID 41201961, 2025).
glioma (continued). "Simultaneously, LRIG1 modulates the Bcl-2 and Topo-2 levels, rendering glioma cells more responsive to temozolomide (TMZ) treatment." (PMID 38790164, 2024). "Integration of 5hmC data revealed a strong positive correlation in the glioma tissue group between 5hmC and the gene expression of the LRIG1 gene." (PMID 38790164, 2024). "Specifically, gene LRIG1 had an average mean log fold-change (logFC) of 5.07 in the glioma samples and 1.27 in the normal samples, with a significant difference (p-value 2.02 × 10−11)." (PMID 38790164, 2024). "From a therapeutic perspective, restoring LRIG1 levels in tumors, particularly gliomas, has emerged as a promising strategy for suppressing receptor-positive tumors." (PMID 38790164, 2024). "LRIG1 has been reported to be a haploinsufficient inhibitor of platelet-derived growth factor-induced glioma." (PMID 33893245, 2021). "Down-regulation of LRIG1 aggravates the aggressive properties of glioma cells by activating the EGFR pathway." (PMID 30487162, 2019). "Third, variants in CCDC26 (the 8q24 locus), C2orf80 (close to IDH), LRIG1, PHLDB1, ETFA, MAML2 and ZBTB16 were associated with IDH-mutant glioma." (PMID 31842352, 2019). "In other reports, the glioma cell line SHG-44 transfected with pEGFP-Cl-LRIG1 and overexpressing LRIG1 inhibits VM promoted by hypoxia as well as migration, invasion, and proliferation." (PMID 31993365, 2019). "This was demonstrated by the experiment revealing that Lrig1 KO mice developed higher grade gliomas than did wild-type mice." (PMID 31358815, 2019). "In melanoma, LRIG1 shows the same effects as glioma, but these are mediated by blocking via EGFR/ERK signaling." (PMID 31993365, 2019). "Intriguingly, Lrig1-heterozygous mice developed higher grade gliomas than did wild-type mice (grade IV vs. grade II/III, p = 0.002)." (PMID 29391393, 2018). "In the present study, we investigated the role of physiological Lrig1 expression in PDGFB-induced glioma in mice and analyzed the effects of forced LRIG1 overexpression on human glioblastoma xenografts in vivo and on human glioblastoma cells in vitro." (PMID 29391393, 2018). "Nevertheless, our results show that LRIG1 suppresses the migration of glioma cells in a cell context-dependent manner partially via MET inhibition." (PMID 29391393, 2018). "The relationship between the physical ZBTB16-LRIG1 interaction and the functions of LRIG1 and ZBTB16 in glioma susceptibility remains an important area for future research." (PMID 29317492, 2018). "In summary, Lrig1 is a haploinsufficient suppressor of PDGFB-driven glioma, possibly in part via negative regulation of MET-driven cell migration and invasion." (PMID 29391393, 2018). "Accordingly, LRIG1 overexpression in the primary human glioma cell line TB107 suppressed glioma invasion in vivo and cell migration in vitro." (PMID 29391393, 2018). "Intriguingly, single nucleotide polymorphisms in both the LRIG1 and ZBTB16 genes are associated with glioma susceptibility." (PMID 29317492, 2018). "Reciprocally, the ectopic expression of LRIG1 in the TB107 high-grade human glioma (glioblastoma, grade IV) cell line decreased the invasion of orthotopic tumors in immunocompromised mice in vivo and reduced cell migration in vitro." (PMID 29391393, 2018). "Lrig1 was expressed in PDGFB-induced gliomas in wild-type mice as assessed using in situ hybridization." (PMID 29391393, 2018). "In summary, our novel finding that Lrig1 is a haploinsufficient tumor suppressor gene in glioma provides a possible functional link between the SNP rs11706832 and the etiology of diffuse glioma." (PMID 29391393, 2018). "To further analyze the effects of LRIG1 overexpression on the migration of glioma cells, we transduced TB101 and TB107 cells with a doxycycline-inducible LRIG1 allele and analyzed their migration with or without the induction of ectopic LRIG1 expression." (PMID 29391393, 2018).
glioma (continued). "The soluble LRIG1 ectodomain is demonstrated to be shed naturally and inhibit the progression of glioma." (PMID 25353163, 2014). "The phenotype of Lrig2E12-/- mice showed that Lrig2 was a promoter of PDGFB-induced glioma, and Lrig2 appeared to have important molecular and developmental functions that were distinct from those of Lrig1 and Lrig3." (PMID 24023893, 2013). "However, we also found a significantly increased expression in grade II glioma compared to the surrounding tissue, which differs from LRIG1 but is in line with the previous described linkage to low grade glioma." (PMID 41201961, 2025). "Furthermore, the comparison of gene expression across different cancers showed the highest upregulation of LRIG1 in glioma." (PMID 38790164, 2024). "The intersection of gene lists that showed positive differences in 5hmC levels between glioma and normal/healthy samples resulted in two promising candidate genes: leucine-rich repeats and immunoglobulin-like domains protein 1 (LRIG1) and zinc finger protein 703 (ZNF703)." (PMID 38790164, 2024). "Notably, gene LRIG1 demonstrated a significant upregulation in the glioma tissue compared to normal brain tissue." (PMID 38790164, 2024). "Interestingly gene LRIG1 also exhibited a strong positive correlation with gene expression data in glioma patients." (PMID 38790164, 2024). "The glioma risk SNP rs11706832 is located in intron 2 of LRIG1, but this study found no apparent effect on LRIG1 expression level in the genetically modified HEK293T cell lines." (PMID 37185361, 2023). "In conclusion, the data in this and previous studies suggest that the increased risk of IDH1-mutated glioma conferred by rs11706832 is not caused by an effect on the LRIG1 expression level." (PMID 37185361, 2023). "Moreover, previous studies have also shown that LRIG1 exerts anti-oncogenic effects by inhibiting cell invasion, migration and proliferation in glioma cell microenvironment." (PMID 33893245, 2021). "Also, recombinant LRIG1 ectodomain suppresses cell proliferation in glioma cells, both in vitro and in vivo." (PMID 33947959, 2021). "Analogously, overexpression of LRIG1 also inhibited hypoxia-induced VM in glioma cells." (PMID 30487162, 2019). "Furthermore, we observed a significant association between the genetic variants in LRIG1, PHLDB1, ETFA, ZBTB16 and MAML2 and the risk of IDH-mutant glioma." (PMID 31842352, 2019). "Risk variants in LRIG1, PHLDB1, ETFA, MAML2 and ZBTB16 were also associated with IDH-mutant glioma." (PMID 31842352, 2019). "Here, we investigated the role of Lrig1 in platelet-derived growth factor (PDGF)-induced experimental glioma in mice by introducing mono-allelic and bi-allelic deletions of Lrig1 followed by inducing gliomagenesis via intracranial retroviral transduction of PDGFB in neural progenitor cells." (PMID 29391393, 2018). "Additionally, a soluble form of the LRIG1 ectodomain can inhibit EGFR signaling in trans as well as suppress the proliferation of glioma cells in vitro and the growth of human glioma xenografts in vivo." (PMID 29391393, 2018). "The soluble LRIG1 ectodomain was proved to inhibit the glioma cell proliferation recently." (PMID 25353163, 2014). "LRIG3 appears to have a similar role to LRIG1 in the progression of glioma." (PMID 25353163, 2014). "Moreover, this soluble LRIG1 ectodomain has been shown to inhibit the genesis and progression of glioma in vivo." (PMID 25353163, 2014). "Previous studies describe that LRIG1 may enhance chemo-sensitivity of glioma cells." (PMID 41201961, 2025). "The ectodomain of LRIG1 has been used as a soluble compound in patient-derived glioblastoma models in vivo with promising results, and the drug resveratrol has been found to inhibit glioma cell growth and promote its apoptosis by upregulating LRIG1 gene expression." (PMID 34331569, 2021).
glioma (continued). "Thus, it can be hypothesized that LRIG1 may suppress glioma growth by enhancing BMP signaling, in addition to its previously proposed regulation of RTK signaling." (PMID 33469151, 2021). "Indeed, the ectodomain of LRIG1 can be shed from full-length LRIG1 after proteolytic cleavage both in vitro and in vivo and recombinant LRIG1 ectodomain has been demonstrated to suppress tumor growth in a mouse glioma model." (PMID 33947959, 2021). "The LRIG1 genetic risk variant is located in intron 2, relatively close to exon 3, where differential mRNA splicing is one potential functional mechanism, but the exact mechanism by which the increased glioma risk is conveyed is not understood." (PMID 31842352, 2019). "More broadly, the results also suggest that other modes of LRIG1 gene regulation, including promoter methylation, histone acetylation, and gene copy number variations, could be highly relevant in gliomagenesis and glioma progression both in children and in adults." (PMID 29391393, 2018). "Because the reduced Lrig1 expression increased the malignancy of low-grade diffuse glioma, we tested the complementary hypothesis, i.e., whether forced LRIG1 overexpression in human high-grade glioma cells (i.e., glioblastoma cells) can reduce their malignancy." (PMID 29391393, 2018). "Thus, LRIG1 may function as a tumor suppressor in glioma by suppressing cellular invasion and migration as well as cellular proliferation in a cell context-dependent manner." (PMID 29391393, 2018). "Therefore, our current demonstration that the LRIG1 expression level is a determinant of the aggressiveness of PDGFB-driven gliomas may be highly relevant to the etiology of human gliomas." (PMID 29391393, 2018). "Thus, it will be important to establish whether rs11706832 truly affects LRIG1 expression and/or whether LRIG1 is regulated by other mechanisms in glioma." (PMID 29391393, 2018). "Therefore, we tested the complementary hypothesis, i.e., whether increasing LRIG1 expression in high-grade glioma cells would reduce their malignancy." (PMID 29391393, 2018). "Moreover, LRIG1 was demonstrated to be a tumor suppressor gene and may be related to glioma chemotherapy resistance, such as was observed in our present study, in a manner that could be reversed by miR-20a." (PMID 26337869, 2015). "LRIG1, as the most studied LRIG protein, showed significantly lower expression levels in glioma compared to healthy patients." (PMID 41201961, 2025). "The expression negatively correlated with WHO tumor grade, both LRIG1 and LRIG2 were decreased in high grade glioma." (PMID 41201961, 2025). "The intersection of gene lists derived from these comparative analyses unveiled LRIG1 and ZNF703 as the two genes with elevated 5hmC levels in both the cfDNA of glioma patients and gDNA of glioma tissue compared to their respective controls." (PMID 38790164, 2024). "Through pairwise group comparisons and a subsequent intersection of gene lists, we identified two genes, LRIG1 and ZNF703, exhibiting higher 5hmC levels in glioma patients/tissues when compared to healthy individuals/normal brain tissue." (PMID 38790164, 2024). "In our current study, we identified genes LRIG1 and ZNF703 with 5hmC gene levels higher in both the cfDNA and gDNA of glioma patients." (PMID 38790164, 2024). "In summary, miR‐19 promotes glioma cell migration mainly through the negative regulation on RUNX3, RhoB and LRIG1." (PMID 30073755, 2018). "To address the role of LRIG1 in PDGF-driven gliomas, we used the RCAS/Ntv-a system to induce glioma in mice with different Lrig1 genotypes via the intracranial transduction of neural progenitor cells with PDGFB-encoding RCAS viruses." (PMID 29391393, 2018). "The feasibility and efficacy of the inhibitory effects of LRIG1 on tumor through inhibiting EGFR signaling activity have been studied in renal cancer, glioma, squamous cell carcinoma of skin, colorectal cancer and prostate cancer." (PMID 24314030, 2013).